ERBB2 (erb-b2 receptor tyrosine kinase 2)
Diseases named in the same sentence as ERBB2 in open-access papers (continued):
Sharing a sentence is not in itself a finding about the gene and the disease.
cancer (continued). "Conceivably, treatment of ErbB2-positive cancers could be facilitated by use of agents blocking oncogenic signaling mechanisms downstream of ErbB2." (PMID 35933456, 2022). "Conversely, these two types of cancers showed a remarkable ERBB2 deficiency, suggesting that ERBB2 overload is not a crucial cause of some cancers, even though 67% of pan-cancers have presented a high ERBB2 gene level." (PMID 36172165, 2022). "However, when the ERBB2 expression in cancer is impaired compared with the matching normal tissue, the ATM level increases compared with the matching normal tissue, as illustrated in colon, kidney renal clear cell and kidney renal papillary cell cancers." (PMID 36056635, 2022). "ERBB2 enrichment indicates a poor prognosis in some cancer types but could be a favorable prognostic factor in others." (PMID 36172165, 2022). "Conceivably, treatment efficacy of ErbB2-positive cancers could be facilitated by drugs blocking oncogenic mechanisms downstream of ErbB2." (PMID 35933456, 2022). "This chromatin remodelling revealed that the HNF4A and PPARGC1A regulated transcriptional regulatory networks play a pivotal role in promoting the emergence of drug resistant cancer cells and represent potential therapeutic targets to enhance the efficacy of ERBB2 inhibition strategies." (PMID 36153371, 2022). "Besides, the prognosis of these patients harbored ERBB2 amplification only was better than those with ERBB2 fusions combination with amplification in pan-cancer." (PMID 36276102, 2022). "Oleic acid may suppress the over-expression of HER2 (erbB-2), an oncogene which plays a key role in the invasive progression and metastasis in several human cancers." (PMID 36263307, 2022). "Overall, ERBB2 mutation did not activate cancer-associated fibroblast cluster as messengers between the innate and adaptive immune systems." (PMID 36172165, 2022). "ERBB2 gene promoter demethylation activated an immunity mechanism and enhanced protein translation in a non-canonical manner, which is a critical factor in the poor prognosis of cancer patients." (PMID 36172165, 2022). "In view of the crucial role of ERBB2 in the immune microenvironment and metabolic reprogramming of pan-cancer, the important relationship of the ERBB2 gene and its protein product HER2 with the immune and metabolic regulation of GC was extensively investigated." (PMID 35990657, 2022). "Importantly, the ERBB2 (HER2) gene, a key factor in cell proliferation in cancer but also involved in adipocyte differentiation, is simultaneously hypermethylated at its 5′ UTR and overexpressed in PCOS cells compared to control." (PMID 35269469, 2022). "Overexpressed ERBB2 is the primary therapeutic target for cancer." (PMID 35937803, 2022). "Most ERBB2 fusions are accompanied by ERBB2 amplification and may play a role in the prognosis of pan-cancer, especially BRCA." (PMID 36276102, 2022). "In addition, the close relationship between GG and AAG metabolism-related genes and ERBB2 expression was validated at the pan-cancer transcriptomic level." (PMID 35990657, 2022). "ERBB2 amplifications fell most frequently in breast (15.9%) and stomach (8.3%) cancers." (PMID 35911441, 2022). "Thus far, the majority of the studies related to ERBB2 in cancers have focused on identifying the landscape of genomic amplification in ERBB2 and defining therapeutic regimens to target these amplifications." (PMID 36612126, 2022). "Interestingly, combining all the differentially expressed genes of invasive fibroblasts for IPA analysis uncovered the cancer metastasis-related regulatory pathways in which the ERBB2 (HER2) signaling pathway was most activated in invasive fibroblasts." (PMID 35980387, 2022). "However, in primary cancer samples, ERBB2 mean increase to 8.1 with a decrease of ATM to 8.4 (p < 0.0001)." (PMID 36056635, 2022). "The ERBB2–MAPK pathway has been extensively studied in cancer." (PMID 36605402, 2022).
cancer (continued). "Among these, CPNE3 (copine-3) was demonstrated to interact with ERBB2 through a receptor dependent manner and it may be a novel factor regulating the ERBB2-dependent cancer cell motility." (PMID 35685794, 2022). "Our results may have important implications for elucidating the activating mechanisms of ERBB2 ECD variants and for defining a model workflow for analyzing VUS detected by cancer gene panel tests." (PMID 34997908, 2022). "Furthermore, CDK4/6 inhibitors and PIK3CA inhibitors are standard of care for advanced luminal carcinomas, and ERBB2-low expression has been recently reported as an independent predictor of inferior progression-free survival." (PMID 36038884, 2022). "Furthermore, post-trastuzumab tumors had a deletion of ERBB2 exon 16, resulting in a hyperphosphorylated ERBB2 isoform that is described to be resistant against ERBB2-targeted therapies in cancer models." (PMID 34503107, 2021). "Cancers that are HR–/ERBB2– are referred to as triple-negative breast cancer (TNBC)." (PMID 33670942, 2021). "Furthermore, high‐level amplifications targeting cancer‐critical genes, including the therapeutic targets ERBB2 and EGFR, were also typically homogeneously present within patients, both among multiple metastatic lesions and in the primary tumor." (PMID 33325154, 2021). "Since the ERBB2-expressing cancer cell lines, BT474, SKBR3, MDA-MB-361, MCF7, and OE19, used by the other studies also express EGFR, the lapatinib-induced autophagy promotion reported by these studies may be due to lapatinib inhibition of EGFR." (PMID 33801244, 2021). "In addition, scRNA-seq revealed upregulation of several cancer-associated (Il-4/Il-13, Hsf1/HSP), oncogenic (TGFβ, NGF, FGF, MAPK) and self-renewal (Wnt, Notch) pathways in p63+/−;ErbB2 luminal cells and PIMECs per se." (PMID 34023861, 2021). "Among patients with ERBB2-positive cancer treated with trastuzumab, those with a higher than the median morphology–based H&E-ERBB2 score derived from machine learning had more favorable DDFS than those with a lower score (hazard ratio [HR] 0.37; 95% CI, 0.15–0.93; P = 0.034)." (PMID 33597560, 2021). "The MET signaling pathway can be activated by multiple molecules, plexins, integrins, EGFR, and ERBB2, and the crosstalk between those pathways may contribute to cancer progression and drug resistance." (PMID 34761497, 2021). "Met signaling cross-talked/cross-linked with other signaling downstream from several membrane receptors such as RON, EGFR and ErbB2 and could assume a mechanism of resistance for cancer progression." (PMID 33918490, 2021). "Furthermore, CHD4 expression reduction affects cancer cell’s autophagy process as well as the ERBB2 gene, which is an epithermal growth factor member, resulting in a drug resistance effect." (PMID 34142021, 2021). "It is well documented that FOXP3, as a critical master transcription regulator for Treg cell development and function, helps control the activities of various genes (such as oncogenes SKP2 and HER-2/ErbB2) related to the cancer development of the breast and prostate." (PMID 34768829, 2021). "Expression of the tyrosine kinase receptor ERBB2 in cancer cells leads to drug resistance." (PMID 33801244, 2021). "Nowadays, ErbB2-targeted therapy is one of the most effective in cancer treatment." (PMID 34944558, 2021). "Recently, accumulating evidences showed that ErbB2 shuttles into the nucleus and plays important roles in a variety of cellular processes, such as proliferation, signal transduction, and resistance to cancer therapy." (PMID 33854045, 2021).
cancer (continued). "Interestingly, the CNN trained in the current study was not only a statistically significant and an independent predictor of the ERBB2 status but also identified patients with CISH ERBB2-positive cancer who benefited more from trastuzumab." (PMID 33597560, 2021). "In addition, we show that germline ERBB2 variants are more frequently identified in individuals with an MPN phenotype compared to those with other hematologic malignancies and non-cancer controls." (PMID 34209587, 2021). "A high H&E-ERBB2 score was associated with unfavorable survival in patients with ERBB2-negative cancer as determined by CISH." (PMID 33597560, 2021). "Combined treatment with anthracyclines (e.g., doxorubicin; Dox) and trastuzumab (Trz), a humanized anti-human epidermal growth factor receptor 2 (HER2; ErbB2) antibody, in patients with HER2-positive cancer is limited by cardiotoxicity, as manifested by contractile dysfunction and arrhythmia." (PMID 33897465, 2021). "Moreover, the alteration in expression levels of other molecules such, c-MET, RAS/BRAF, EGFR/ERBB2 which are involved downstream, affect cancer cell proliferation and development." (PMID 33777535, 2021). "All together, these observations suggest that some of the CISH ERBB2-negative patients might potentially benefit from anti-ERBB2 treatment and those can be detected via analyzing conventional H&E-stained cancer tissue samples." (PMID 33597560, 2021). "Moreover, an increase of the ErbB2 expression level has also been seen in bladder, pancreas, ovarian, colon, kidney, esophagus, prostate and other types of cancer." (PMID 34944558, 2021). "ERBB2+ cancer cells release EVs displaying this orphan receptor on the membrane." (PMID 33809102, 2021). "In summary, germline coding variants in ERBB2 are more common among individuals with MPN than individuals without cancer." (PMID 34209587, 2021). "The available evidence indicated that the transactivation of HER2 (known as ErbB2) by S1P could promote cancer progression through subsequently activating the PI3K/Akt and Ras/MEK signaling pathways." (PMID 34831211, 2021). "Furthermore, knockdown of ErbB2 in Cdc25A-transfected cells inhibited the increased viability mediated by Cdc25A overexpression in sorafenib-treated cancer cells." (PMID 34743185, 2021). "Additionally, the copy number status of known cancer genes was also consistent between exome and cancer panel, including the expected ERBB2 amplification which was correctly determined in all cases." (PMID 33208147, 2020). "For ERBB2-positive cancers (16/82 [20%]), adjuvant trastuzumab was prescribed for a year." (PMID 33107920, 2020). "As far as mammary oncogenesis is concerned, it has also been shown that ErbB2 and PyVT may regulate cancer stem cells and cancer stem cell pathways." (PMID 33196707, 2020). "Similarly, after adjusting for income quintile, grade, ERBB2 status, and age, ER-negative cancers had significantly higher odds than ER-positive cancers of being interval compared with screen-detected cancers (OR, 2.88; 95% CI, 2.01-4.13)." (PMID 32975573, 2020). "ERBB2 mutation may also be correlated with mutation of E-cadherin (CDH1), a glycoprotein that mediates adhesion between epithelial cells and suppresses cancer invasion." (PMID 31980423, 2020). "The KRT6A-positive subset of mammary epithelial cells can be induced to form cancer by ErbB2." (PMID 33221741, 2020). "The cellular uptake of the anti-cancer drugs could be considerably improved through receptor-mediated endocytosis when the drugs were delivered to ErbB2-overexpressing cells by the immunoliposomes." (PMID 32599712, 2020). "Finally, ERBB2 mRNA expression was explored in 392 BCs from an in-house dataset, 368 primary BCs from the TCGA BC dataset, and 10,071 tumors representing 33 cancer types from the PanCancer TCGA dataset." (PMID 32674482, 2020). "ErbB2-targeting liposomes with rapamycin effectively inhibited the growth of BT-474 cancer cells." (PMID 32599712, 2020).
cancer (continued). "No small-molecule inhibitor is currently approved for cancers harboring oncogenic ERBB2 point mutations." (PMID 32366937, 2020). "Probably, the top-scoring network predicted in this study might uncover the non-genomic estrogen-dependent downstream effect orchestrated by ERBB2 in these female-specific cancers." (PMID 33424936, 2020). "Moreover, studies in cancer cells and patient samples show that when ErbB2 is overexpressed, it translocates from the plasma membrane to mitochondria." (PMID 32655416, 2020). "Cancer cells that overexpress EGFR and/or ErbB2 are susceptible to their inhibition by Lapatinib." (PMID 33348877, 2020). "ERBB2/Her2-neu gene amplification occurs in a wide variety of human cancers." (PMID 32552660, 2020). "Furthermore, the impact of ERBB2 mRNA levels on T-DM1 benefit has been reported in other cancers beyond BC." (PMID 32674482, 2020). "Moreover, ErbB2 can form heterodimers with IGF-IR in IGF-IR inhibitor-resistant cancer cells, leading to the induction of ErbB2 phosphorylation by IGF2." (PMID 32493414, 2020). "NRGs belong to the large family of EGF ligands, and are implicated in brain development activities by interacting with ErbB and regulating HER2, HER3, and HER4 (ERBB2, ERBB3 and ERBB4, respectively, in mice), all of which have been linked to different types of cancers in the literature." (PMID 32341755, 2020). "In addition, several reports have showed that some gene mutations, like BRAF mutation and ERBB2 mutation, were associated with MSI status in several cancer types." (PMID 33178590, 2020). "The activation of the ERBB2 signaling pathway can induce autophagy in a variety of cancers." (PMID 32649310, 2020). "ERBB2 is a ligand-less tyrosine kinase receptor expressed at very low levels in normal tissues; when overexpressed, it is involved in malignant transformation and tumorigenesis in several carcinomas." (PMID 33037285, 2020). "In ERBB2-amplified cancers, additional analysis of both p95HER2 and full-length HER2 components may have important therapeutic implications." (PMID 31442103, 2019). "Understanding the molecular biology of WIP1 inhibitors could increase the potency of WIP1 inhibitors in a specific subsets of tumors with PPM1D/RPS6KB1 and ERBB2 co-amplification that may lead to improved cancer care." (PMID 31827209, 2019). "Furthermore, CD151-integrin complexes seemed to be involved in protecting cancer cells in the special case of drugs targeting ErbB2." (PMID 30778617, 2019). "Erbicin-derived immunoagents (EDIAs) were found to be selectively cytotoxic for ErbB2-positive cancer cells (including those resistant to Trastuzumab) in vitro and in vivo, to recognize an epitope different from that of Trastuzumab and Pertuzumab, and not to be cardiotoxic." (PMID 31470510, 2019). "Additionally, ERBB2 and ERBB3 gain-of-function mutations have been shown to contribute to the occurrence and development of a variety of cancers." (PMID 31752936, 2019). "Among them, up-stream tyrosine kinase receptor ErbB-2, Rab-like protein 6 (RABL6), microphthalmia-associated transcription factor (MITF), which are involved in progression and development of several types of cancer were predicted to be suppressed." (PMID 31671612, 2019). "Several proteins including HSP90, flotillin, and caveolin have been shown to regulate the cell surface distribution of ErbB2, but how cholesterol content in cell membrane regulates the overall surface presence of this cancer-driving receptor tyrosine kinase remains elusive so far." (PMID 30786890, 2019). "However, the affinity of the loop in domain II of ErbB2 for its homodimerization is low and the homodimerization of ErbB2 requires its upregulation, which is frequently induced by amplification of ERBB2 in various cancers, including breast cancer." (PMID 31831814, 2019).
cancer (continued). "Amplification of the oncogenes ERBB2, CDK6, MDM2 affected dependency, as did point mutations in PIK3CA, KRAS, NRAS, VHL and BRAF, validating our approach to highlight genes with significance in cancer." (PMID 30803482, 2019). "ERBB2 is a gene frequently altered in different types of cancer." (PMID 31116314, 2019). "ERBB2 gene amplification was most frequently identified in patients with gastric (21.4%; 6/28), colorectal (11.1%; 5/45), lung (3.9%; 9/231), and breast (3.2%; 1/31) cancers." (PMID 31019892, 2019). "ErbB-1 (also known as EGFR, epidermal growth factor receptor) and ErbB-2 (also known as HER2, human epidermal growth factor receptor 2), are famous therapeutic targets for cancer treatment and their excessive signaling play critical roles in the development and malignancy of many tumors." (PMID 31510100, 2019). "Alterations in the expression of specific HER2 species in ERBB2-amplified cancers, including p95HER2, may have therapeutic implications and require further investigation." (PMID 31442103, 2019). "In addition, CLCN3 promotes 3D spheroid proliferation in ErbB2-overexpressing breast epithelial and cancer cells." (PMID 31608175, 2019). "Indeed, functional enrichment analysis by Enrichr in our study found that these genes were enriched in the basic cancer-related biological processes, including mitotic recombination, DNA metabolism, and ErbB2 signaling pathway." (PMID 31572431, 2019). "In this study, we examined the HER2/c-erbB-2, EGFR expression in cancer and normal gastric tissue of 67 patients with gastric carcinomaby immunohistochemistry assay and explored the correlation between HER2/c-erbB-2, EGFR expression and clinicopathological features and prognosis." (PMID 33817143, 2019). "Moreover, numerous cell-surface tyrosine kinase receptors (RTK), including EGFR, FGFR, PDGF, c-MET, ERBB2/HER2, and IGFR are known to be regulated by cancer-associated glycans, glycosyltransferases, and proteoglycans." (PMID 31157165, 2019). "In addition, in early stage cancer the ERBB2 amplicon is composed of a single segment, while in advanced stage cancer it is composed of several different segments." (PMID 31827209, 2019). "Motivated by all these findings, we have designed and synthesised a series of pyrazolo[3,4-d]pyrimidines as novel small molecules targeting both EGFR and ErbB2 tyrosine kinases to be useful for treatment of cancer via inhibition of cell growth and induction of apoptosis." (PMID 30688116, 2019). "HER2 (Human Epidermal Growth Factor Receptor II) or ERBB2 (Avian erythroblastosis oncogene B), encoded at chromosome 17q21, is a well-defined tyrosine kinase receptor often acting as proto-oncogene in many human cancers." (PMID 30205505, 2018). "Interestingly, ErbB2 also activates signaling molecules regulating metabolism and mitochondrial function and promotes cancer cell growth and glycolysis which are reduced by trastuzumab." (PMID 29743983, 2018). "In addition, A19 internalizes into cancer cells that have high expression levels of Erbb-2 and thus is useful as an antibody drug conjugate (ADC) to kill these cells in vitro." (PMID 30072783, 2018). "The erbB2 gene is amplified in approximately 20–35% of human breast cancers and other cancer types." (PMID 30607328, 2018). "ERBB2 is a plasma membrane-bound receptor tyrosine kinases that is involved in the protection of cardiac myocytes, which is illustrated by the cardiotoxicity of ERBB2-targeted cancer therapies." (PMID 29556499, 2018). "Hence, A19 has the potential to be developed as an alternative targeted therapeutic agent for cancers expressing Erbb-2." (PMID 30072783, 2018).